PAX2 (paired box 2)
Diseases named in the same sentence as PAX2 in open-access papers (continued):
Sharing a sentence is not in itself a finding about the gene and the disease.
coloboma (continued). "LOH affecting FADD was reported in ocular coloboma; since PAX2 mutations have been identified as one of the most common causes of coloboma, it could be speculated that reduced FADD expression—either due to LOH or to mutations in PAX2 causing regulation of transcription—would play a role in coloboma." (PMID 31569512, 2019). "Moreover, the coloboma score was significantly higher in patients with PAX2 gene mutations." (PMID 26571382, 2015). "Previous research has linked mutations in genes such as CHX10, MAF, PAX6, PAX2, RX (RAX), SHH, SIX3, OTX2, and SOX2 to phenotypes associated with microphthalmia, anophthalmia, and coloboma (MAC)." (PMID 39129019, 2024). "The third patient was a neonate in whom PAX2-related disorder manifested as oligohydramnios, coloboma, and renal failure that progressed to ESRD within 1 year after birth." (PMID 35087773, 2022). "These included the known human coloboma associated genes (indicated by #): SMOC1, PAX2, VAX1 and ALDH6, in addition to the coloboma candidates from other animal studies CHRDL1 and CYP1B1 (indicated by •)." (PMID 31162046, 2019). "One possible explanation for the development of colobomas is that the decreased level of Rybp in the mutant retinas influences the normal distribution of regulatory proteins such as Pax6 or Pax2." (PMID 17470285, 2007). "PAX2 abnormalities can lead to renal problems and ocular coloboma but few of the other features of CHARGE syndrome have been observed in such children." (PMID 16959034, 2006). "Among the nine patients with RCS in this study, five patients did not screen for any fundus diseases until identifying the PAX2 variants, who were subsequently diagnosed with unilateral coloboma." (PMID 34696790, 2021). "Among the molecules that are involved in coloboma formation is the transcription factor Pax2." (PMID 28729440, 2017). "In addition, a genetic signaling cascade for coloboma centered around PAX2 has been elucidated involving SHH and BMP4 signaling as upstream regulators." (PMID 24412933, 2014). "Further studies suggest that PAX2 mutations are not common in patients with isolated ocular coloboma and associated anomalies." (PMID 21655361, 2011). "At first, this result appeared contradictory, as Pax2 loss of function and/or haploinsufficiency, rather than a gain of function, has been associated with the formation of colobomas, microphthalmia and optic nerve defects in both humans and animals." (PMID 20485507, 2010). "PAX2 malformations have been associated with optic nerve coloboma, SIX6 mutations with bilateral anophthalmia and pituitary abnormalities as well as microphthalmia, CHX10 mutations with microphthalmia, and SHH mutations with human microphthalmia and coloboma." (PMID 19158959, 2009). "Among these were the known human MAC genes TENM3, SMOC1, PAX2, ALDH1A3, and BMPR1B, in addition to NID1, VAX1, and NTN1, which have been previously identified as MAC or coloboma candidates based on animal studies." (PMID 36830662, 2023). "The most commonly identified genetic causes of isolated coloboma, without microphthalmia, are CHD7 (OMIM 608892) mutations associated with CHARGE syndrome (OMIM 214800) and PAX2 mutations, which cause renal-coloboma syndrome (OMIM 167409)." (PMID 24412933, 2014). "Finally, increased Pax2 and Vax2 labeling at the site of the choroid fissure in the morphant-injected embryos compared to control-injected embryos suggests delayed closure of the optic fissure and may implicate these genes and/or the Pax2 pathway in the pathogenesis of the colobomas." (PMID 20485507, 2010). "Underdiagnosis of eye lesions in patients might be attributed to the lack of awareness of PAX2-related disorder, especially in patients without any complaints of poor eyesight who were diagnosed with unilateral coloboma." (PMID 34696790, 2021).
endometrial cancer (21 papers, 2009 to 2025). Primary or metastatic malignant neoplasm involving the endometrium (mucous membrane that lines the endometrial cavity). "Our study highlights the potential clinical applications of Akt, mTOR, and Pax-2 as diagnostic markers in endometrial cancer screening." (PMID 40357279, 2025). "The aberrant loss of nuclear expression of PAX2 occurs in approximately 70–80% of endometrial carcinoma and AH/EIN." (PMID 38539494, 2024). "CTNNB1 point mutations are early events in endometrial carcinoma development, making β-catenin (along with PAX2 and PTEN) a plausible biomarker for endometrioid precancers." (PMID 38539494, 2024). "Similarly in breast cancer, expression of PAX2 has been associated with a low invasive phenotype in luminal breast cancer cells, while in endometrial cancer joint loss of PAX2 and PTEN expression was associated with progression to carcinoma." (PMID 29928489, 2018). "We demonstrated that PAX2 is an endometrial tumor suppressor recurrently inactivated by a distinct epigenetic reprogramming event in more than 80% of human endometrial cancers." (PMID 40829174, 2025). "IHC expression of Akt, mTOR, and Pax-2 was positively correlated with ICC expression within the endometrial carcinoma cohort, benign lesion cohort, and normal cohort." (PMID 40357279, 2025). "ASH2L is involved in promotion of endometrial cancer progression via upregulation of PAX2 transcription." (PMID 37974198, 2023). "On the other hand, growing studies have shown that PAX2 acts as an oncogenic gene in diverse cancers, such as endometrial cancer and ovarian cancer." (PMID 35028121, 2022). "In endometrial cancer, it activates tumor cell proliferation and migration, and upregulates PAX2 (an oncogene of endometrial cancer) transcription." (PMID 36553510, 2022). "In line with evidence on the role of PAX2 in endometrial cancer, we studied the effect of downregulating expression levels of PAX2 in Ishikawa cells using a mix of specific siRNAs that produced a marked reduction of its transcript and protein." (PMID 35018885, 2022). "(A) PAX2 expression in Non Tumor (normal endometrium) and two histologically distinct endometrial cancer samples." (PMID 35018885, 2022). "Dysgulated expression of PAX2 has been linked to several cancer types, including RCC, ovarian cancer, endometrial cancer, prostate cancer, breast cancer, melanoma, medulloblastoma and Wilms tumor." (PMID 29928489, 2018). "MassARRAY analysis indicated that the PAX2 promoter was hypermethylated in endometrial cancer tissues and cell lines." (PMID 27764784, 2016). "Because PAX2 expression was increased in endometrial cancer tissues compared with normal endometrium, we assumed that PAX2 played an oncogenic role in the carcinogenesis of endometrial cancer." (PMID 27764784, 2016). "PAX2 expression was reportedly lost in 73.3% of G1 endometrioid endometrial cancers and in 77% of endometrial cancers, and this pattern correlated with pathological malignancy and PTEN deletion." (PMID 27764784, 2016). "After treatment, the methylation level of the PAX2 promoter decreased in endometrial cancer cell lines (HEC-1A: from 94.6% to 55.4%, RL95-2: from 59% to 48%, HEC-1B: from 96% to 66%." (PMID 27764784, 2016). "We identified a repressive regulatory region of the PAX2 promoter in endometrial cancer cells by cloning the 5’ flanking region." (PMID 27764784, 2016). "As an oncogene involved in the development of endometrial cancer, PAX2 is activated in the development of tamoxifen-induced endometrial cancer, which is related to hypomethylation-induced activation." (PMID 27764784, 2016). "In conclusion, PAX2 is involved in the carcinogenesis of endometrial cancer by stimulating cell growth and promoting cell motility." (PMID 27764784, 2016).
endometrial cancer (continued). "PAX2 expression was increased in the epithelium of endometrial cancers compared with hyperplasia and normal endometrium." (PMID 27764784, 2016). "PAX2 is a downstream gene in the steroid hormone receptor signal pathway and is overexpressed in endometrial cancer and benign endometrial hyperplasia compared with normal controls." (PMID 27764784, 2016). "PAX2 was overexpressed in endometrial cancer cells compared with primary cultured EECs, which was consistent with the immunohistochemistry results." (PMID 27764784, 2016). "The overexpression of PAX2 in endometrial cancer is regulated by promoter hypermethylation and the transcription factor MZF1." (PMID 27764784, 2016). "In renal malignancies, the overexpression of PAX2 is regulated by DNA hypomethylation, which also occurs in tamoxifen-induced endometrial cancer and endometriosis." (PMID 27764784, 2016). "We further investigated the function of PAX2 and showed that it acted as a tumor promoter by promoting cell proliferation, migration and invasion in endometrial cancer cell lines." (PMID 27764784, 2016). "This work investigated the role of paired box 2 (PAX2) in endometrial cancer and its epigenetic regulation mechanism." (PMID 27764784, 2016). "Some articles suggest that PAX2 is an oncogene in the development of endometrial cancer, but others consider it to be a tumor suppressor gene." (PMID 27764784, 2016). "We found that PAX2 was involved in endometrial cancer by stimulating cell growth and promoting cell motility." (PMID 27764784, 2016). "This study investigated the role and defined the promoter region that regulated the expression of PAX2 through DNA methylation and upstream transcription factors in endometrial cancer." (PMID 27764784, 2016). "PAX2 overexpression in endometrial cancer was regulated by promoter hypermethylation via the transcription factor MZF1." (PMID 27764784, 2016). "Endometrial cancer tissues and cell lines exhibited increased PAX2 expression compared with hyperplasia, normal endometrium and endometrial epithelial cells." (PMID 27764784, 2016). "Altogether, these evidences suggest that PAX2 plays a crucial role in the determination of tamoxifen response both in breast and endometrial cancer cells, by repressing and promoting cell proliferation, respectively." (PMID 23192763, 2013). "The expression of ER, PR, IGF-1R, β-catenin and PAX-2 have been immunohistochemically investigated in 86 type I endometrial cancer specimens." (PMID 24308813, 2013). "PAX2 is a common target of estrogen- and tamoxifen-bound ER and is a crucial effector for the proliferation of endometrial cancer cells." (PMID 23192763, 2013). "These include R-RAS and MASP in GC, MAGE1 in melanoma, S100A4 in colon cancer, PAX2 in endometrial cancer, DNMT3A in testicular germ cell tumours, and various genes in pancreatic cancer." (PMID 19107131, 2009). "This study aimed to detect the expression of Akt, mTOR, and Pax-2 in differing endometrial tissue/cells, together with assessment of such molecular markers for improving accuracy within endometrial cytology screening for endometrial cancer (EC)." (PMID 40357279, 2025). "The mechanism of this loss is poorly understood, as PAX2 is not one of the frequently mutated genes identified in endometrial carcinoma." (PMID 38539494, 2024). "PAX2 is a known oncogenic gene in endometrial cancer, it is an estrogen-induced target gene." (PMID 35197930, 2022). "Unlike Pten and β-catenin, which are frequently mutated in endometrial cancers and precancers, PAX2 mutations have not been reported in endometrial cancers." (PMID 35798968, 2022). "The effect of methylation on MZF1-targeted DNA binding motifs has previously been described for the reprogramming key gene OCT4 in induced pluripotent stem cells, the PAX2 gene in endometrial cancer, and the tumour antigen PRAME (preferentially expressed antigen in melanoma) in melanoma cells." (PMID 35409379, 2022).
endometrial cancer (continued). "PAX2 was found to be constantly expressed in most epithelial cells of non-neoplastic tissues of Müllerian origin but less frequently observed in several types of endometrial cancer." (PMID 27764784, 2016). "Abnormal expression of PAX2 also occurs in endometrial cancer." (PMID 27764784, 2016). "In gynecological diseases, PAX2 is hypomethylated in tamoxifen-induced endometrial cancer." (PMID 27764784, 2016). "However, in contrast to the general rules of DNA methylation, we found the opposite result that PAX2 mRNA and protein levels were up-regulated in endometrial cancer." (PMID 27764784, 2016). "Indeed, the mechanism of abnormal PAX2 expression in endometrial cancer, which we address in this study, is rarely reported." (PMID 27764784, 2016). "Conflicts exist in the studies of PAX2 in endometrial cancer." (PMID 27764784, 2016). "This contradictory result indicates that PAX2 may play a complex role in the development of endometrial cancer and may be due to the different genetic backgrounds among studies, differences in the antibody binding domains or insufficient sample sizes." (PMID 27764784, 2016). "Increased methylation levels of the PAX2 promoter were observed in endometrial cancer cell lines." (PMID 27764784, 2016). "Furthermore, PAX2 is silenced in normal endometrium, and its expression is reactivated in endometrial cancer upon hypomethylation of its promoter." (PMID 23192763, 2013). "Conversely, PAX2 promoter methylation has been found in normal endometrium lacking Pax-2 expression and its loss has been associated with Pax-2 re-expression in endometrial carcinoma." (PMID 23890189, 2013). "However, the underlying mechanisms behind this loss are not well understood, given that Pax-2 is not among the genes frequently mutated in endometrial carcinoma." (PMID 40357279, 2025). "To elucidate whether the expression of PAX2 is regulated by DNA methylation, we first investigated the methylation status of the PAX2 promoter in endometrial epithelial cells (EECs) and endometrial cancer cell lines and in 3 endometrial tissue samples by bisulfite sequencing." (PMID 27764784, 2016). "However, other articles have reported that PAX2 expression is decreased in endometrial cancer." (PMID 27764784, 2016). "In a xenotransplanted tumor model of human endometrial cancer in nude mice, increased PAX2 expression was observed in tumors with poor cell differentiation, and tumor volume as well as expression of PCNA and Bcl-2 were decreased following knockdown of PAX2." (PMID 27764784, 2016). "Additionally to the established role of estrogen and progesterone in hyperplasia induction and endometrial cancer onset, are other factors also involved in the development of this cancer, which include IGF-1R, β-catenin and PAX-2." (PMID 24308813, 2013). "They stated that tamoxifen and estrogen could activate PAX2 mRNA expression in endometrial cancer cell lines but not in normal endometrial samples." (PMID 32300484, 2020). "Regardless, the function of PAX2 in endometrial cancer has not been clarified to date." (PMID 27764784, 2016). "Although PAX2 and GATA3 may also stain positive in a small subset of endometrial carcinomas, including EC, they are mostly negative and were only focally and weakly positive in adenocarcinomas of Mullerian origin." (PMID 34441384, 2021).
renal cell carcinoma (17 papers, 2011 to 2025). "Here we show that TGF-β1 treatment of renal cell carcinoma cells is associated with transcriptional supression of PAX2, through the direct binding of SMAD proteins to the PAX2 promoter." (PMID 29928489, 2018). "While most PAX8+ and PAX2+ carcinomas are rarely confused with melanoma, cases of MiTf family altered renal cell carcinoma (MiTF-RCC) may pose a diagnostic challenge owing to the frequent patchy expression of melanocytic markers." (PMID 34449584, 2021). "PAX2 is expressed in multiple different cancer types, including in renal cell carcinoma (RCC), ovarian cancer, endometrial carcinoma, breast cancer, and prostate cancer." (PMID 29928489, 2018). "Over-expression of PAX2 beyond embryogenesis only appears to be seen in pathological conditions, including renal cell carcinomas, polycystic kidney disease and Wilms’ tumour." (PMID 23565707, 2013). "Renal cell carcinoma cells usually exhibit positive expression of PAX2, EMA, CD10, Cam5.2, and AE1/3, whereas ovarian tumor cells exhibit positive expression for CK7, CA125, and ER/PR." (PMID 23227402, 2012). "PAX2 expression is often restricted to embryogenesis and is down-regulated in adults but is reexpressed in several tumors like Wilms tumor, renal cell carcinoma, breast cancer and karposi sarcoma." (PMID 21876729, 2011). "PAX2 immunohistochemistry has shown to be a sensitive marker for diagnosing nephrogenic adenomas and renal cell carcinoma." (PMID 21826275, 2011). "However, it is noteworthy that PAX2 was found to be reactivated in renal cell carcinoma and that around 90% of renal cell carcinoma patients have high PAX2 and PAX8 expression levels." (PMID 38928435, 2024). "On the other hand, PAX2 is expressed in ovarian cancer, renal-cell carcinomas (RCC) and in some bladder carcinomas, where it is crucial for tumor survival since PAX2 regulates the surface protein metallopeptidase, A Disintegrin and metalloproteinase-domain containing protein 10 (ADAM10)." (PMID 31614829, 2019). "ADAM10 is regulated by transcription factor PAX2 in renal cell carcinoma and melanoma cells." (PMID 30117015, 2018). "Almost thirty years ago, scientists proved that the inactivation of PAX2 by different approaches, such as antisense oligonucleotides, small interfering RNA (siRNA) or small hairpin RNA (shRNA), results in the growth inhibition of human renal cell carcinoma in vitro." (PMID 37628926, 2023). "Here we have investigated direct regulation of PAX2 expression by TGF-β1 in clear cell renal cell carcinoma (CC-RCC) cell lines." (PMID 29928489, 2018). "We have identified a direct role for SMAD proteins in binding to the PAX2 gene promoter to suppress PAX2 expression in human clear cell renal cell carcinoma (CC-RCC) cells, during canonical TGF-β signalling." (PMID 29928489, 2018). "This intronic transcript is anti-sense to the developmental transcription factor PAX2, a gene whose function is essential during embryonic development and morphogenesis but whose overexpression also contributes to the pathogenesis of diseases such as renal cell carcinoma and medulloblastoma." (PMID 23565812, 2013). "The mechanisms by which PAX2 induces EMT are still not well understood, although some studies have suggested that PAX2 regulates ADAM10 expression in cancer cell lines including renal cell carcinoma and melanoma." (PMID 30117015, 2018). "Immunohistochemical analysis with a panel of kidney-specific markers (AQP1, PAX2, and CK7) demonstrated that these tumors were renal cell carcinomas." (PMID 26418749, 2015).
renal cell carcinoma (continued). "In metastatic ccRCC, commonly expressed immunohistochemical markers include CD10, PAX-2, PAX-8, human kidney injury molecule-1 (hKIM-1), renal cell carcinoma monoclonal antibody (RCCma), von Hippel–Lindau (VHL) tumor suppressor gene products, EMA, E-cadherin, and S-100 protein." (PMID 39931206, 2024).